ENSG00000272741 (novel protein)
Gene: Protein-coding gene on chromosome 3 (196,248,230 to 196,318,222, reverse strand). Ensembl gene ENSG00000272741.
Genetic constraint (gnomAD): Missense variants: 102 observed, 107.71 expected, observed/expected ratio (o/e) 0.95, 90% interval 0.81 to 1.12. Synonymous variants: 54 observed, 38.33 expected, observed/expected ratio (o/e) 1.41, 90% interval 1.13 to 1.76.